Y_RNA (Y RNA )
Gene: Miscellaneous RNA gene on chromosome 1 (85,435,175 to 85,435,284, reverse strand). Ensembl gene ENSG00000199459.
Homologues: Orthologues: chimpanzee Y_RNA (100% identical), macaque Y_RNA (95% identical). Paralogues in human: RNY1P5 (85% identical), Y_RNA (85% identical), Y_RNA (82% identical), RNY1 (81% identical), Y_RNA (81% identical), Y_RNA (80% identical), Y_RNA (79% identical), Y_RNA (78% identical), RNY1P1 (77% identical), Y_RNA (77% identical), RNY1P11 (76% identical), RNY1P14 (76% identical), and 94 more.